CD4 (CD4 molecule)
Diseases named in the same sentence as CD4 in open-access papers (continued):
Sharing a sentence is not in itself a finding about the gene and the disease.
autoimmune myocarditis (28 papers, 2014 to 2025). Autoimmune myocarditis is an autoimmune disease that affects the heart. "CD4+ T cell immunometabolic dysfunction is associated with experimental autoimmune myocarditis progression." (PMID 38201290, 2023). "Tarrio has described that a αMyHC peptide can successfully induce the susceptibility of autoimmune myocarditis (with CD4+ and CD8+ T-lymphocyte infiltration) in PD-1 deficient mice." (PMID 35517794, 2022). "Autoimmune myocarditis (AM) is primarily mediated by CD4+ T cells, with Th1 and Th17 cell infiltrates being identified in the hearts of murine models." (PMID 40176976, 2025). "It was previously shown that PGK1 inhibition with NG52 treatment attenuates autoimmune myocarditis in mice through suppressing CD4+ T cell activation and differentiation into Th17 cells." (PMID 40260243, 2025). "This is consistent with previous research indicating that CD4 T cell responses play a critical role in driving autoimmune myocarditis." (PMID 39075540, 2024). "In the present study, we established an experimental autoimmune myocarditis (EAM) model in BALB/c mice and evaluated the effects of acacetin on cardiac injury and heart function and CD4+ T cell-associated immune responses in EAM mice." (PMID 38741130, 2024). "Further studies are warranted to investigate the role of ICAM-1 in cardiac homing of CD4+ T lymphocytes during the pathological process of autoimmune myocarditis." (PMID 37901475, 2023). "CD4+ T lymphocyte homing is considered the initiating event in autoimmune myocarditis, which is highly dependent on ICAM-1." (PMID 37901475, 2023). "Several observations support a role of CD4+ T cells as major drivers of autoimmune myocarditis development." (PMID 37627502, 2023). "Autoimmune myocarditis is considered immunologically to be a CD4+ T lymphocyte-mediated immune damaging disease." (PMID 37901475, 2023). "To address the properties of exosomes under inflammatory conditions, we used the mouse model of CD4+ T cell-dependent experimental autoimmune myocarditis." (PMID 36211827, 2022). "This phenomenon is also reproduced in a CD4+ T-cell-dependent model of autoimmune myocarditis, in which PD-1 absence enhanced cardiac damage." (PMID 35433707, 2022). "The differentiation of T cell subsets in normal mice was induced, and pathological CD4+ T cells were inhibited to achieve a therapeutic effect on autoimmune myocarditis." (PMID 34838003, 2021). "Autoimmune myocarditis secondary to the immune infiltration of CD4+ T cells into the heart is a rare but often fatal event associated with checkpoint-inhibitor immunotherapy." (PMID 34638410, 2021). "On the other hand, the deletion of PD-1 in Murphy Roths Large (MRL) mice led to lethal autoimmune myocarditis with massive CD4+ and CD8+ T-lymphocytes infiltration." (PMID 32244307, 2020). "In this study, we also addressed their contribution also to the development of autoimmune myocarditis and found that Rock1+/− and Rock2+/− developed unaffected CD4+ T cell-mediated cardiac inflammation." (PMID 32178482, 2020). "Heart-infiltrating CD4+ T cells in TCR-M mice suffering from spontaneous autoimmune myocarditis, also showed a mixed Th1/Th17 cytokine profile." (PMID 30524444, 2018). "Several observations support a role for CD4+ T cells as major drivers of autoimmune myocarditis development." (PMID 30035131, 2018). "Further investigation is needed to determine whether PD-L2 in CD4+ T cells is involved in the development and progression of autoimmune myocarditis." (PMID 33572655, 2021). "In autoimmune myocarditis progression, CD4+ T-lymphocytes serve as the main driving force." (PMID 32244307, 2020). "However, as CD4+ T cells are considered to be the major driver of autoimmune myocarditis, our data support the idea that vaccine-induced myocardial inflammation is a consequence of excessive CD4+ T-cell infiltration, and thus, a potential driver of autoimmunological myocardial damage." (PMID 35805941, 2022).
autoimmune myocarditis (continued). "In a mouse model, depleting CD4+CD25+Foxp3+ regulatory T cells (Tregs) leads to severe multi-organ inflammation, and, similar to EAM, to autoimmune myocarditis with high-titers of anti-myosin autoantibodies." (PMID 24586934, 2014). "Here, using mouse models of experimental autoimmune myocarditis (EAM) we investigated the role of heart non-specific CD4+ T cells in the progression of the disease." (PMID 31863205, 2019). "Furthermore, NG52 inhibited the activation and differentiation of CD4+ T cells, suggesting that PGK1 may play a key role in the metabolic regulation of T cell differentiation and autoimmune myocarditis." (PMID 39712033, 2024).
Chlamydia infection (28 papers, 2008 to 2025). "Low CD4 count (< 350 cells/mm3) and previous chlamydia infection were associated with an increased risk of carcinogenic HPV infection among HIV-infected MSM in Northern California." (PMID 38148878, 2023). "In order to understand the contribution of these CD4 T cells and other non-CD4 sources of IFN-γ during Chlamydia infection, we infected IFN-γ- and IFN-γR1-deficient mice vaginally with C. muridarum." (PMID 35196366, 2022). "Given the capacity of T-bet-deficient mice to efficiently resolve Chlamydia infection, we examined the effector response of CD4 T cells in these mice in more detail." (PMID 35196366, 2022). "On the other hand, clustering associated more weakly with Chlamydia infection (from p = 0.013 to p = 0.097), CD4 cell counts (from p = 0.002 to p = 0.022) and presentation during acute infection (from p = 0.017 to p = 0.120)." (PMID 20822507, 2010). "Univariate analysis additionally showed strong association with Chlamydia infection (p < 0.001), acute stage of infection at initial presentation (p < 0.001) and higher CD4+ T cell count (p = 0.001)." (PMID 20822507, 2010). "Moreover, the susceptibility of these B cell-deficient, CD4+ depleted mice to Chlamydia infection suggests a relationship between CD4+ T cells and B cells in providing protective immunity." (PMID 25386180, 2014). "Interestingly, CD4 T cells in T-bet-deficient mice displayed a profound shift towards Th17 responses, suggesting compensation between these two CD4 effector subsets in the control of Chlamydia infection." (PMID 35196366, 2022). "Research indicates that CD4+ T cells are essential in expediting Chlamydia clearance and preventing reinfection, playing a pivotal role during Chlamydia infection." (PMID 41190885, 2025). "In the adaptive immune stage, IFN-γ secreted by Th1 (CD4+) cells is the core effector against Chlamydia infection, while CD8+ T cells become the key force to control the proliferation of Chlamydia by secreting IFN-γ." (PMID 41156830, 2025). "After the antibody blocks the function of CD8+ T cells and CD4+ T cells, the symptoms of Chlamydia infection are significantly aggravated, affecting the prognosis, and IFN-γ is the main effector." (PMID 41156830, 2025). "Murine studies have shown that CD4 T-cell–secreted IFN-γ is a key component of a protective antibody response in Chlamydia infection: IFN-γ appears to be necessary for activating effector cells that function in antibody-mediated immunity to reinfection." (PMID 39436737, 2025). "During a natural Chlamydia infection, the inflammatory cytokine IFNγ is produced by the innate immune response as well as CD4 +T cells and is thought to have a protective effect against infection." (PMID 39804088, 2025). "Here we show that mice with CD4 T cells that lack the capacity to secrete IFN-γ still resolve Chlamydia infection of the FRT." (PMID 38166152, 2024). "The T cell-intrinsic requirement of Bhlhe40 prompted us to identify the essential CD4 T cell effector functions controlled by Bhlhe40 during Chlamydia infection." (PMID 38271477, 2024). "Together, these data make a compelling case for a reassessment of CD4-effector immunity in Chlamydia infection." (PMID 38166152, 2024). "Previous studies have identified Chlamydia-specific IFN-γ+IL-17A+ CD4 T cells in the FRT following Chlamydia infection or vaccination." (PMID 38271477, 2024). "Together, our data suggest that an IL-12p40-dependent protective CD4 module emerges to combat Chlamydia infection that is distinct from well-described Th1 and Th17 effectors." (PMID 38166152, 2024). "In summary, our study provides compelling evidence that a multifaceted CD4 T cell response in Chlamydia infection is essential for protective immunity." (PMID 38271477, 2024). "Protection against Chlamydia infection requires not only neutralizing antibodies but also IFN-γ-producing CD4+ T-cells." (PMID 39066427, 2024).
Chlamydia infection (continued). "Chlamydia infection in the FRT drives a potent CD4 T cell expansion in the secondary lymphoid organs and recruits both antigen-specific and bystander CD4 T cells to the site of infection." (PMID 38271477, 2024). "The proportion of mice shedding bacteria at any given point during Chlamydia infection was also comparable between CD4-Cre Tbx21f/f mice and littermate controls." (PMID 35196366, 2022). "Foundational work from several laboratories has determined that CD4 T cells are the critical lymphocyte population that orchestrate clearance of Chlamydia infection from the female reproductive tract." (PMID 35196366, 2022). "In the case of Chlamydia infection, it is widely believed that CD4 Th1 cells are the major effector lineage that orchestrates bacterial clearance from the reproductive tract." (PMID 35196366, 2022). "Previous work has established that IFN-γ is a common component of the CD4 T cell response to Chlamydia infection of the FRT." (PMID 35196366, 2022). "The importance of IFN−γ−secreting CD4+ T cells during Chlamydia infection has previously been demonstrated in both human clinical and experimental animal model studies." (PMID 34249004, 2021). "A number of experiments from Salmonella and Chlamydia infection models suggest that early antibiotic intervention impedes the development of effective protective memory, which is largely mediated by Th1 CD4 cells." (PMID 27999159, 2016). "Overall, our data provide important insight into the ability of antibody to protect after CD4+ T cell priming of the genital tract during initial Chlamydia infection." (PMID 27600502, 2016). "Together, these data point to a major role for CD4 Th1 cells in primary clearance of both Salmonella and Chlamydia infections." (PMID 27999159, 2016). "Here, we describe the generation of peptide-MHC class II tetramers that allow direct visualization of endogenous, polyclonal antigen-specific CD4 T cell responses to Chlamydia infection." (PMID 24204262, 2013). "This is consistent with previous reports that Th1 CD4 T cells are the dominant helper subset following Chlamydia infection." (PMID 24204262, 2013). "Our interest in Chlamydial HtrA was triggered by the fact that Chlamydia infection induces HtrA-specific CD4+ T cells both in humans and in mice." (PMID 24009891, 2013). "Genital Chlamydia infection of mice enhanced Ag-specific Abs in serum and vaginal secretions as well as proliferative cytokine responses by CD4+ T cells isolated from systemic and mucosal compartments." (PMID 18700040, 2008). "Moreover, the key molecules that drive the differentiation of protective CD4 T cells in Chlamydia infection remain to be identified." (PMID 38271477, 2024). "Experiments are currently underway to evaluate whether Chlamydia infection induces cytotoxic function in the polyfunctional CD4 T cells in vivo and whether these cells contribute to protective immunity." (PMID 38271477, 2024). "The mechanism that CD4 T cells use to mediate clearance of Chlamydia infection in the female reproductive tract remains unclear." (PMID 38166152, 2024). "CD4 T cells in human Chlamydia infection secrete significant levels of IFN-γ." (PMID 38166152, 2024). "Our data show that non-Th1 CD4 T cells secrete IFN-γ in the FRT during Chlamydia infection." (PMID 35196366, 2022). "Since Th1 cells are defined by the expression of the master transcription factor T-bet (Tbx21), we hypothesized that IFN-γ-producing CD4 T cells responding to Chlamydia infection would express T-bet." (PMID 35196366, 2022). "Similarly, recent data show that MyD88 expression in CD4 T cells is important for the resolution of Chlamydia infection from the genital tract independently of TLR or IL-1R." (PMID 28817719, 2017).
Chlamydia infection (continued). "Recent studies have shown that repeated use of antibiotics to control a primary Chlamydia infection induces effector memory CD4 T cells in local draining lymph nodes, but the relationship between this population and effective protective immunity has not been established." (PMID 27999159, 2016). "However, in both mouse models of Salmonella and Chlamydia infection, pathogen-specific CD4 Th1 cells have been found to be essential for successful resolution of primary infection." (PMID 25071779, 2014). "Thus, the development of pathogen-specific CD4 Th1 cells is essential for the development of protective immunity in mouse models of Salmonella and Chlamydia infection." (PMID 25071779, 2014). "Future vaccine efforts for Chlamydia infections should refrain from focusing on inducing Chlamydia-specific Th1 or Th17 cells, since the appropriate module that allows elimination of Chlamydia from epithelial cells is a distinct CD4 T cell maturation pathway and remains to be identified." (PMID 38166152, 2024). "Thus, vaginal Chlamydia infection drives robust CD4 IFN-γ production within the FRT." (PMID 35196366, 2022). "Thus, deficiency in secondary protective immunity to Salmonella and Chlamydia infection seems likely to involve CD4 T cell memory and may reflect an alteration in generating a specific protective subset." (PMID 27999159, 2016). "The absence of CCR2 exacerbates C. muridarum infection in the respiratory tract by impairing the differentiation of CD4+ T cells into Th1 cells and reducing IFN-γ secretion, thereby weakening the immune response to Chlamydia infection." (PMID 39903705, 2025). "Acquired immunity to Chlamydia is mediated by CD4+ T-cells producing Th1 type cytokines such as IFN-γ, which are considered correlates of protective immunity in human Chlamydia infections." (PMID 30374357, 2018). "Transferred Th1 cells responding to peptide immunization were visualized using CD90.1+Salmonella-specific SM1 TCR transgenic CD4 T cells (SM1), while endogenous CD90.2+ CD4 T cells responding to Chlamydia infection were monitored simultaneously." (PMID 28817719, 2017). "Ultimately, antigens that are capable of inducing CD4+ T cells with Th1-biased cytokines, mainly IFN-γ, along with humoral responses, can induce optimal responses for protection against Chlamydia infections and would be highly desirable." (PMID 29295593, 2017). "Although both CD4+ and CD8+ T cells contribute protective immunity during Chlamydia infection, differences exist depending on the model of Chlamydia and the mode of infection studied." (PMID 25386180, 2014). "Genital Chlamydia infection up-regulated Ab responses as well as splenic and ILN CD4+ T cell proliferative responses." (PMID 18700040, 2008). "Several studies on Chlamydia infection have shown that many cells can produce IFN-γ, including natural killer T (NKT) cells, Th1 (CD4) or Th1-like (such as CD8) cells, NK (killer ILC1s), ILC1s (helper ILC1s), Ex-ILC3s, mucosal-associated invariant T (MAIT) cells, and even some myeloid cells." (PMID 41156830, 2025). "Although Th17 cells are required for rapid resolution of Chlamydia infection, our data also suggests that complete clearance of Chlamydia occurs in mice lacking either of the three common CD4 modules (Th1, Th2 and Th17)." (PMID 38166152, 2024). "MHC class II-restricted CD4 Th1 responses are believed to be vital for bacterial clearance due to their capacity to secrete IFN-γ, but an essential requirement for T-bet-expressing Th1 cells has yet to be demonstrated in the mouse model of Chlamydia infection." (PMID 35196366, 2022). "Consistent with the absence of CD4 T-bet expression in the FRT, CD4-Cre Tbx21f/f mice resolved Chlamydia infection with similar kinetics to Cre-negative littermate controls." (PMID 35196366, 2022).
Chlamydia infection (continued). "Their role in Chlamydia infection, although still not completely resolved, seems to be very modest and is therefore most likely not responsible for the CD4 independent protection we observe in the present study." (PMID 20505822, 2010). "Thus, mice lacking T-bet, STAT6, or CD4-derived IFN-γ can fully resolve Chlamydia infection in the FRT." (PMID 38166152, 2024). "Furthermore, loss of T-bet expression in CD4 T cells, or in other host cells, did not completely eliminate IFN-γ production or impede the ability of mice to clear Chlamydia infection from the FRT." (PMID 35196366, 2022). "Similarly, mice lacking MHC class II-restricted CD4 T cells or IFN-γ have difficulty resolving primary Chlamydia infection, and yet, CD8 T cells or B cells are not essential." (PMID 27999159, 2016). "Thus, peak expansion of IFN-γ-secreting CD4 cells closely mirrored peak bacterial burdens in vivo, and stable Chlamydia-specific CD4 T cell memory frequencies were maintained in the absence of active Chlamydia infection." (PMID 24204262, 2013). "Since T-bet-deficient mice lacking Th1 cells fully resolved Chlamydia infection of the FRT, it was of interest to determine whether this clearance required IFN-γ, since T-bet-independent pathways of CD4 IFN-γ production have been detected in other infection models." (PMID 35196366, 2022). "Recent work has shown Chlamydia infection of the gastrointestinal tract in wild-type mice and that IFN-γ from CD4 T cells clears Chlamydia from the small intestine, but not from the large intestine." (PMID 38166152, 2024). "Given the virtual absence of T-bet expression among Chlamydia-specific CD4 T cells within the FRT of infected mice, we explored whether T-bet expression was required to resolve Chlamydia infection." (PMID 35196366, 2022). "Paraffin-embedded endometrial tissues from uninfected women and women with extantendometrial Chlamydia infection (but no other identified genitaltract infection) were stained with polyclonal antibodies detecting GATA-3 or T-bet(both Abcam) and/or a monoclonal antibody detecting CD4 (Dako)." (PMID 23555586, 2013).